DVL1 (dishevelled segment polarity protein 1)
Diseases named in the same sentence as DVL1 in open-access papers (continued):
Sharing a sentence is not in itself a finding about the gene and the disease.
autism (2 papers, 2014 to 2024). Persistent deficits in social interaction and communication and interaction as well as a markedly restricted repertoire of activity and interest as well as repetitive patterns of behavior. "Mice null for Dvl1 have diminished social interactions, a core feature of autism, as well as abnormal prepulse inhibition, which is observed in both autism and schizophrenia." (PMID 24672476, 2014).
cervical cancer (2 papers, 2013 to 2023). A primary or metastatic malignant neoplasm involving the cervix. "Herein, we observed that DVL3, but neither DVL1 nor DVL2, was significantly up-regulated and associated with augmented Wnt/β-catenin signaling activity and cervical cancer cell growth." (PMID 23301094, 2013).
diabetes (2 papers, 2016 to 2018). "With regards to diabetes, methylation at CpGs in the body of DVL1 has been associated with the development of T2D, and expression of DVL1 is reduced in adipose tissue of non-diabetic subjects with insulin resistance compared to controls." (PMID 30212457, 2018).
liver cancer (2 papers, 2020 to 2023). An epithelial or non-epithelial malignant neoplasm that arises from the liver. "Recent studies link Wnt9A polymorphism to HCC risk, Wnt7B to sorafenib resistance, and DVL1 to Wnt activation and poor prognosis liver cancer." (PMID 38036507, 2023). "Additionally, expression of Disheveled, DVL1, a key regulator of Wnt pathway activation, was significantly higher in liver cancer cells with low DDX5 expression, from two independent cohorts." (PMID 33042264, 2020).
lobular breast carcinoma (2 papers, 2007 to 2021). "The DVL1 gene encoding protein involved in Wnt signaling and the leucine-rich repeat protein ASPN (asporin) were upregulated in lobular carcinomas." (PMID 17389037, 2007). "Immunohistochemistry confirmed higher expression of DVL1 and EMP1 in lobular carcinomas and of DDR1 in ductal carcinomas (p < 0.0001)." (PMID 17389037, 2007).
meningioma (2 papers, 2021 to 2024). A generally slow growing tumor attached to the dura mater. "The samples containing mutations in the PDZ domain expressed significantly less DVL1 protein product, and the nuclear expression of DVL1 could potentially represent a good biomarker for meningioma progression and the activation of the Wnt signaling pathway." (PMID 34769425, 2021). "In 48% of the analyzed meningiomas, the nuclear expression of DVL1 was missing; however, 22% of the samples still showed DVL1 expression in more than 50% of the nuclei." (PMID 34769425, 2021). "Although it is well known that the Wnt signaling pathway is involved in meningioma progression, the role of its central mediator, DVL1, is still unclear." (PMID 34769425, 2021). "The nuclear expression of DVL1 was found to correlate significantly with high expression of active β-catenin and meningioma grade, suggesting that DVL1 may serve as a biomarker for meningioma progression and Wnt pathway activation." (PMID 39594618, 2024). "This may suggest that the nuclear expression of DVL1 could promote Wnt signaling activation and potentially serve as a biomarker of meningioma progression." (PMID 34769425, 2021). "The same study indicated that high-grade tumors had a lower expression of DVL1, suggesting that it may be an early event, which is contrary to our present findings on meningioma." (PMID 34769425, 2021). "Therefore, in future meningioma studies, samples could be tested with two DVL1 gene microsatellite markers to show if a higher frequency of genomic instability is present." (PMID 34769425, 2021). "Additionally, the substitution of T (g.13921T>C) could be a marker of low DVL1 expression in higher grade meningioma patients." (PMID 34769425, 2021). "Our present results showed that the LOH of DVL1 was not tied to the malignant grade and may represent early event in meningioma progression." (PMID 34769425, 2021). "Furthermore, our study showed that the cytoplasmic expression of DVL1 was not correlated with meningioma grade or the expression of active cytoplasmic β-catenin (r = 0.101, p = 0.647)." (PMID 34769425, 2021).
neuroblastoma (2 papers, 2016 to 2018). Neuroblastoma (NB) is the most common solid, extracranial childhood tumor. "In this study, for the first time, we identified Dvl1 as a Ngb-binding protein, and showed that Ngb inhibits Wnt/β-Catenin and increases NFκB signaling pathway via regulating degradation of Dvl1 protein in human neuroblastoma SK-N-SH cells." (PMID 30041403, 2018). "To test this hypothesis, we transiently co-transfected neuroblastoma (SH-SY5Y) cells with constructs harboring human DVL1, DVL2 or DVL3 with a FLAG epitope tag in the N-terminus and EGFP in the C-terminus." (PMID 27008544, 2016).
neuroendocrine tumors (2 papers, 2023 to 2024). "In conclusion, this study underscores the significant involvement of SFRP3 and DVL1 in the development and progression of neuroendocrine tumors." (PMID 39796676, 2024). "This retrospective study investigated the serum levels of LRP6, SFRP3, and DVL1 in patients with neuroendocrine tumors (NETs) and a control group using the ELISA method." (PMID 39796676, 2024). "The significant variation in DVL1 concentrations across different primary tumor sites underscores the complexity of neuroendocrine tumors and the need for a nuanced approach to their study and treatment." (PMID 39796676, 2024). "The aim of this study was to evaluate and compare the serum concentrations of LRP6, SFRP3, and DVL1 between patients with neuroendocrine tumors (NETs) and healthy individuals, and to correlate these findings with selected demographic, clinicopathological, and biochemical characteristics." (PMID 39796676, 2024). "Importantly, Dvl1-dependent degradation of Sstr2 can be stimulated by overexpression of Wnts and treatment of cells with Wnt pathway inhibitors can boost Sstr2 expression in neuroendocrine tumor cells." (PMID 36965619, 2023). "There are currently no studies on the concentration of DVL1 in patients with neuroendocrine tumors, nor have any been conducted using animal models to explore this connection." (PMID 39796676, 2024). "This indicated that the DVL1 concentration is not uniform across the different types of neuroendocrine tumors and may reflect the unique biological characteristics of tumors originating in different organs." (PMID 39796676, 2024).
ovarian carcinoma (2 papers, 2017 to 2021). A malignant neoplasm originating from the surface ovarian epithelium. "Hypermethylation of genes like ASS1, MLH1, and MSX1, and WNT pathway-related genes including DVL1, NFATC3, and SFRP5 was related to poor outcome of ovarian cancer patients treated with platinum-based chemotherapy." (PMID 28641578, 2017).
Parkinson disease (2 papers, 2020 to 2024). A progressive degenerative disorder of the central nervous system characterized by loss of dopamine producing neurons in the substantia nigra and the presence of Lewy bodies in the substantia nigra and locus coeruleus. "If probes are simply ranked according to uncorrected p value, this co-localization enrichment increases to include 17 and 14 of the top-20 probes for the hypothalamus and eye, respectively, and includes additional transcripts of interest such as Dvl1 (Wnt signaling) and Park7 (Parkinson’s disease)." (PMID 32116548, 2020).
schizophrenia (2 papers, 2013). A major psychotic disorder characterized by abnormalities in the perception or expression of reality. "It is tempting to speculate that DVL1 gene abnormalities may underlie some of the complex behavioural abnormalities encountered in schizophrenia, such as impaired response to startling and social interaction deficit, but this is currently unlikely to apply to all patients with schizophrenia." (PMID 24403877, 2013).
alveolar rhabdomyosarcoma (1 paper, 2022). A rapidly growing malignant mesenchymal neoplasm. "Importantly, DVL1 and DVL3 also regulate proliferation in alveolar rhabdomyosarcoma (ARMS) cells." (PMID 35589804, 2022).
basal cell carcinoma (1 paper, 2020). A carcinoma involving the basal cells. "Indeed, the genes driving the basal cell carcinoma pathway are FZD9, FZD7, FZD2, DVL1, and AXIN1, all playing a role in the Wnt signaling pathway, which has already been linked to AD and PD." (PMID 33362460, 2020).
bladder cancer (1 paper, 2021). "Altogether, this result showed that ATF5 promoted tumorigenic capability of bladder cancer cells by directly binding and promoting DVL1 to stimulate the Wnt/β-catenin pathway." (PMID 34895217, 2021). "In summary, these results showed that ATF5 overexpression in BLCA was positively related to DVL1 expression, which in turn stimulated Wnt/β-catenin pathway to promote tumorigenic capability of bladder cancer cell." (PMID 34895217, 2021). "Moreover, ATF5 upregulation enhanced DVL1 promoter-driven luciferase activity and DVL1 expression in bladder cancer cells, while ATF5 knockdown exhibited the opposite effects." (PMID 34895217, 2021). "Finally, qRT-PCR and WB analyses were performed to check if the Wnt/ATF5/DVL1 axis in bladder cancer cells is of clinical significant." (PMID 34895217, 2021).
breast invasive carcinomas (1 paper, 2016). "The collective % of alterations in CTNNB1, APC and DVL1 genes among total breast invasive carcinomas were 21% in contrast to 56% breast invasive carcinomas, PAM50 Basal-like." (PMID 27281609, 2016).
Burkitt lymphoma (1 paper, 2017). A rare form of malignant mature B-cell non-Hodgkin lymphoma. "By contrast, in Burkitt's lymphoma, c-Myb is poorly expressed and therefore miR-103 effectuates c-Myc downregulation via targeting of DVL1." (PMID 27888798, 2017).
cerebrovascular disease (1 paper, 2020). "Based on human and mouse phenotype ontologies, DVL1 and AXIN1 were annotated to the “cerebrovascular disease” term and, in particular, with AVM and telangiectasia phenotypes." (PMID 32560555, 2020).
DiGeorge Syndrome (1 paper, 2019). "DVL1 has been reported to be a candidate gene for human development disorder Schwartz‐Jampel syndrome, Charcot‐Marie‐Tooth disease type 2A and DiGeorge Syndrome, while DVL3 have been linked to Hirschsprung's disease." (PMID 30468298, 2019).
ductal carcinomas (1 paper, 2007). "Epithelial membrane protein 1 (EMP1), discoidin domain receptor 1 (DDR1) and human homolog of the Drosophila dishevelled gene (DVL1) were found by pairwise comparison analysis to be differentially expressed between lobular and ductal carcinomas." (PMID 17389037, 2007). "Seven differentially expressed genes (KRT5, KRT6 and KRT17 between tumor and normal cells, CDH1, EMP1, DDR1 and DVL1 between lobular and ductal carcinomas) were verified by immunohistochemical detection of proteins on TMA slides comprising of cores from 119 cases." (PMID 17389037, 2007).
Harel-Yoon syndrome (1 paper, 2022). A syndromic neurodevelopmental disorder characterized by delayed psychomotor development, intellectual disability, truncal hypotonia, spasticity, and peripheral neuropathy. "Referring to the following databases: Berry DB, DECIPHER, OMIM, and DGV, 1p36.33 contains multiple functional genes such as SKI, GNB1, DVL1 and ATAD3A, among which ATAD3A gene is related to Harel-Yoon syndrome, and the possible clinical phenotypes include psychomotor retardation, mental retardation." (PMID 36471261, 2022).
hepatoma (1 paper, 2020). "Intriguingly, FZD10 and LEF1 were only expressed in the medium-differentiated hepatoma but its para-cancer tissues, while a modest expression level of DVL1 in this hepatoma was examined over that of the para-cancer tissues." (PMID 32273945, 2020). "Next, analysis of Wnt/β-catenin signaling components revealed that mRNA expression levels of Wnt5A, CTNNB1P1, DVL1, SMAD4, and JUN were detected in well-differentiated hepatoma but not in their para-carcinoma tissues." (PMID 32273945, 2020).
intracranial meningioma (1 paper, 2021). A meningioma that arises within the cranial cavity. "Our findings concerning alterations of the DVL1 gene in the intracranial meningioma set showed that 15.15% of the samples harbored changes." (PMID 34769425, 2021). "The results of this study contribute to a better understanding of the role of DVL1 in human intracranial meningiomas and point out molecules useful for diagnostics and the treatment of patients." (PMID 34769425, 2021). "In order to investigate the influence of DVL1 gene alterations on the progression of human intracranial meningioma, we focused on its central PDZ domain, which is responsible for DVL interaction with the Fzd receptor and the phosphorylation of DVL mediated through the casein kinases CK1 and CK2." (PMID 34769425, 2021). "The aim of this study was to determine genetic alterations in the DVL1 gene and its central PDZ domain, and their role in the progression of intracranial meningioma." (PMID 34769425, 2021).
invasive carcinoma (1 paper, 2016). A carcinoma that is not confined to the epithelium, and has spread to the surrounding stroma. "Using cBioPortal, here we found that collective % of alteration(s) in WP genes, CTNNB1, APC and DVL1 among breast-invasive-carcinomas was 21% as compared to 56% in PAM50 Basal." (PMID 27281609, 2016).
kidney damage (1 paper, 2021). "Therefore, disturbances of α-tubulin, inversin and DVL-1 found in diseased kidneys might be the underlying pathological mechanism and a result of the switch from noncanonical to canonical Wnt pathway in the developing kidney alluding to the switch between reversible to irreversible kidney damage." (PMID 33800671, 2021).
leukemia (1 paper, 2023). A malignant (clonal) hematologic disorder, involving hematopoietic stem cells and characterized by the presence of primitive or atypical myeloid or lymphoid cells in the bone marrow and the blood. "The resistant leukemia cell lines showed increased transcription levels of WNT/β‐catenin target genes DVL1, GSK3B, and FZD5." (PMID 36567628, 2023).
metastatic tumors (1 paper, 2022). "Moreover, DVL1 and DVL3 expression is increased in metastatic tumors compared to primary NSCLC, and DVL1 expression positively correlates with β-catenin expression metastatic NSCLC." (PMID 35204808, 2022).
nasal polyps (1 paper, 2023). "The expression levels of DVL1, DVL3 and FZD3 mRNAs were significantly lower in the nasal polyps than in the turbinates, while those of FZD6, PRICKLE1, PRICKLE2, VANGL1 and VANGL2 mRNAs were not statistically different between the two tissues." (PMID 38232516, 2023).
nephronophthisis type 2 (1 paper, 2021). "In agreement with that premise, previous studies disclosed that mutation of the inversin gene could result in nephronophthisis type 2, which is mediated by abnormal DVL-1 expression." (PMID 33800671, 2021).
neuropathy (1 paper, 2022). A disorder affecting the nervous system that manifests with pain, tingling, numbness, and/or muscle weakness. "In this study, it was found that PMSCs improved neuropathy in diabetic mice, with the increase of β-catenin and DVL1." (PMID 36440182, 2022).
Obesity (1 paper, 2026). Accumulation of substantial excess body fat. "Dvl1, a core component of the Wnt signaling pathway, has been studied in the context of obesity and NAFLD but remains unexplored in RYGB research." (PMID 41598416, 2026).
osteoarthritis (1 paper, 2025). A noninflammatory degenerative joint disease occurring chiefly in older persons, characterized by degeneration of the articular cartilage, hypertrophy of bone at the margins and changes in the synovial membrane. "Our research aims to investigate the expression of WNT Family Member 5A/B (WNT5A/B), β-catenin, acetyl-α-tubulin, Dishevelled-1 (DVL-1), and Inversin (INV) in the synovial membrane of osteoarthritis (OA) hips." (PMID 40299569, 2025).
pancreatic NETs (1 paper, 2024). "For example, the elevated DVL1 concentrations in pancreatic NETs compared to lung NETs might indicate a higher degree of Wnt signaling pathway activation in pancreatic tumors." (PMID 39796676, 2024). "For instance, DVL1 concentrations were significantly different between pancreatic and lung NETs (p < 0.05), suggesting that the molecular mechanisms involving DVL1 in pancreatic NETs might differ from those in lung NETs." (PMID 39796676, 2024).
pilocytic astrocytoma (1 paper, 2019). Pilocytic astrocytoma is a rare subtype of low-grade glioma of the central nervous system characterized by a well circumscribed, often cystic, brain tumor with a discrete mural nodule and long, hair-like projections that extend from the neoplastic astrocytes. "The lowest frequencies of DVL1 and DVL2 MSI were observed for pilocytic astrocytomas which are benign tumours and not prone to malignant progression." (PMID 30468298, 2019).
rectal cancer (1 paper, 2022). A primary or metastatic malignant neoplasm that affects the rectum. "Evidence suggests that overexpression of the DVL1 gene is closely associated with liver metastasis in rectal cancer." (PMID 36035311, 2022).
renal hypoplasia (1 paper, 2023). Renal hypoplasia is a developmental anomaly in which one or both kidneys (unilateral or bilateral renal hypoplasia, respectively) have a deficit in the number of nephrons and may be small. "Furthermore, β-catenin and cytosolic DVL-1 are upregulated in the postnatal kidneys of yotari mice, implying a switch from non-canonical to overactivated canonical Wnt signaling, which could be another contributing factor to renal hypoplasia in yotari mice or a possible compensatory mechanism." (PMID 37238991, 2023).
rhabdomyosarcoma (1 paper, 2022). A rare aggressive malignant mesenchymal neoplasm arising from skeletal muscle. "Considering the impact of manipulation of DVL1 or DVL3 on skeletal myoblast proliferation, we investigated the role of the DVL proteins in rhabdomyosarcoma." (PMID 35589804, 2022). "DVL1 and DVL3 also contribute to regulation of proliferation in rhabdomyosarcoma." (PMID 35589804, 2022).
sarcoma (1 paper, 2005). A usually aggressive malignant neoplasm of the soft tissue or bone. "The expression of Wnt-1, Dvl-1, 2, 3 and cytosolic β-catenin was analyzed in 6 tissue samples of metastatic sarcoma, A-204 and SJSA-1 cell lines." (PMID 15913453, 2005).
Sepsis (1 paper, 2025). Sepsis is defined as life-threatening organ dysfunction caused by a dysregulated host response to infection. "Among them, Digoxin reduces the level of sepsis-induced oxidative stress by targeting DVL1, thereby improving the survival rate of cardiomyocytes." (PMID 40276499, 2025). "In a broader biological context, this study revealed DVL1 as a key molecular link between sepsis, cancer, and cardiac dysfunction.DVL1 is a core regulator of the Wnt signaling pathway and plays important roles in biological processes such as cell proliferation, differentiation, and migration." (PMID 40276499, 2025). "Although DVL1 is recognized as a key factor in gastrointestinal cancer and SIC, its specific molecular roles and pathways in sepsis, cancer metabolism,and cardiac dysfunction have not been fully explored." (PMID 40276499, 2025).
Spherocytosis (1 paper, 2022). The presence of erythrocytes that are sphere-shaped. "Mutation of Leu to Arg at position 6 in ANK1 protein is associated with Spherocytosis, while Leu to Ser in INVS impairs its ability to target DVL1 for degradation." (PMID 35056738, 2022).
Stroke (1 paper, 2018). Sudden impairment of blood flow to a part of the brain due to occlusion or rupture of an artery to the brain. "Mechanistically, we found that Ngb overexpression increased the levels of Dvl1, an effector of Wnt signaling pathway, and also enhanced the nuclear localization of β-catenin in both cultured NPC and mice brain after stroke." (PMID 30237546, 2018).
testicular tumor (1 paper, 2014). "Altogether, we propose that the testicular tumor in our case might be a phenotypic consequence of the haploinsufficiency of HDAC4 and the duplication of DVL1." (PMID 24755370, 2014).